RBBP8 (RB binding protein 8, endonuclease)
Description:
Endonuclease that cooperates with the MRE11-RAD50-NBN (MRN) complex in DNA-end resection, the first step of double-strand break (DSB) repair through the homologous recombination (HR) pathway. HR is restricted to S and G2 phases of the cell cycle and preferentially repairs DSBs resulting from replication fork collapse. Key determinant of DSB repair pathway choice, as it commits cells to HR by preventing classical non-homologous end-joining (NHEJ). Specifically promotes the endonuclease activity of the MRN complex to clear DNA ends containing protein adducts: recruited to DSBs by NBN following phosphorylation by CDK1, and promotes the endonuclease activity of MRE11 to clear protein-DNA adducts and generate clean double-strand break ends. Functions downstream of the MRN complex and ATM, promotes ATR activation and its recruitment to DSBs in the S/G2 phase facilitating the generation of ssDNA. Component of the BRCA1-RBBP8 complex that regulates CHEK1 activation and controls cell cycle G2/M checkpoints on DNA damage. During immunoglobulin heavy chain class-switch recombination, promotes microhomology-mediated alternative end joining (A-NHEJ) and plays an essential role in chromosomal translocations (By similarity). Binds preferentially to DNA Y-junctions and to DNA substrates with blocked ends and promotes intermolecular DNA bridging.
Synonyms: CtIP; RIM; SAE2; COM1; JAWAD; JWDS; SCKL2
Tractability: PROTAC: UniProt records ubiquitination sites on it; ubiquitination databases record sites on it.
Gene: Protein-coding gene on chromosome 18 (22,798,261 to 23,026,488, forward strand). Ensembl gene ENSG00000101773.
Subcellular location: Nucleus; Chromosome
Subcellular location (Human Protein Atlas): Nucleoplasm
Pathways (Reactome):
DNA Repair: HDR through Homologous Recombination (HRR); HDR through MMEJ (alt-NHEJ); HDR through Single Strand Annealing (SSA); Homologous DNA Pairing and Strand Exchange; Presynaptic phase of homologous DNA pairing and strand exchange; Processing of DNA double-strand break ends; Resolution of D-loop Structures through Holliday Junction Intermediates; Resolution of D-loop Structures through Synthesis-Dependent Strand Annealing (SDSA)
Disease: Defective HDR through Homologous Recombination Repair (HRR) due to PALB2 loss of BRCA1 binding function; Defective HDR through Homologous Recombination Repair (HRR) due to PALB2 loss of BRCA2/RAD51/RAD51C binding function; Defective homologous recombination repair (HRR) due to BRCA1 loss of function; Impaired BRCA2 binding to PALB2; Impaired BRCA2 binding to RAD51
Gene expression (Transcription): Transcriptional Regulation by E2F6
Cell Cycle: G2/M DNA damage checkpoint
Reproduction: Meiotic recombination
Gene Ontology:
Molecular function: damaged DNA binding; identical protein binding; protein binding; RNA polymerase II-specific DNA-binding transcription factor binding; single-stranded DNA endodeoxyribonuclease activity; transcription corepressor activity
Biological process: DNA double-strand break processing involved in repair via single-strand annealing; DNA strand resection involved in replication fork processing; double-strand break repair via homologous recombination; homologous recombination; mitotic G2/M transition checkpoint; DNA repair; negative regulation of DNA-templated transcription
Cellular component: BRCA1-C complex; chromosome; nucleoplasm; nucleus; site of double-strand break; transcription repressor complex
Genetic constraint (gnomAD): Loss-of-function variants: 76 observed, 93.77 expected, observed/expected ratio (o/e) 0.81, 90% interval 0.67 to 0.98. The upper end of that interval is the gene's LOEUF score, 0.98, which puts it in group 4 of 6, group 1 being the genes least tolerant of losing a copy. Missense variants: 958 observed, 1,031.1 expected, observed/expected ratio (o/e) 0.93, 90% interval 0.88 to 0.98. Synonymous variants: 318 observed, 348.41 expected, observed/expected ratio (o/e) 0.91, 90% interval 0.83 to 1.
Homologues: Orthologues: chimpanzee RBBP8 (99% identical), macaque RBBP8 (97% identical), pig RBBP8 (84% identical), guinea pig RBBP8 (80% identical), mouse Rbbp8 (76% identical), rat Rbbp8 (75% identical), dog RBBP8 (72% identical), tropical clawed frog rbbp8 (46% identical), Caenorhabditis elegans com-1 (11% identical). Paralogues in human: RBBP8NL (17% identical).
Diseases named in the same sentence as RBBP8 in open-access papers:
RBBP8 is named in the same sentence as 68 diseases in open-access papers, as found by Europe PMC text mining. Sharing a sentence is not in itself a finding about the gene and the disease. The quoted sentences say what the papers report.
breast carcinoma (26 papers, 2005 to 2025). "According to the risk heatmap, RBBP8 was downregulated in the high-risk group, indicating its tumor suppression potential in breast cancer, and UBE2A acted as a tumor-accelerating gene because it was upregulated in the high-risk group." (PMID 36713553, 2022). "For example, loss of RBBP8 indicated worse prognosis among the breast cancer patients in TCGA and those in the METABRIC." (PMID 33622385, 2021). "On the other hand, RBBP8 functions as a tumor suppressor protein in breast cancer by interacting with some distinct tumor-suppressing factors, including BRCA1 and retinoblastoma." (PMID 36960071, 2023). "The expression level of RBBP8 was lower in M1-stage breast cancer patients than in M0-stage patients." (PMID 36713553, 2022). "The protective role of RBBP8 andPARP3in developing breast cancer, implied by utilizing multivariate Cox regression, was validated." (PMID 36713553, 2022). "The expression level of RBBP8 decreased with ascending T stage, implying its protective role for the breast cancer patient." (PMID 36713553, 2022). "Low RBBP8 expression in many types of tumors (such as bladder cancer, ovarian cancer, and breast cancer) has a worse prognosis." (PMID 30622325, 2020). "They detected significant associations of some haplotypes of BABAM1, ATM, CTIP (RBBP8), TOPBP1, BRIP1, BRE and RAD50 with the modification of breast cancer risk." (PMID 30823486, 2019). "As RBBP8 is a known DNA repair protein that is functionally located in the nucleus (see for instance protein-staining pattern of breast cancer cells), we further focused on nuclear RBBP8." (PMID 29445424, 2018). "To analyze a potential CtIP/RBBP8 relationship with breast cancer clinicopathological variables, we analyzed 384 biopsies obtained during tumor removal surgery between 2004 and 2007 at the University Hospital Virgen del Rocío, Sevilla, Spain." (PMID 24403251, 2013). "We found that the CtIP/RBBP8 level is indeed relevant in the appearance and prognosis of breast cancer." (PMID 24403251, 2013). "We observed a significant link between CtIP/RBBP8 and RB1 expression, as well as a strong relationship between CtIP/RBBP8 levels and specific breast cancer types." (PMID 24403251, 2013). "The stronger link between CtIP/RBBP8 and cancer, and specifically breast cancer, relies in its functional interaction with BRCA1 in DNA repair." (PMID 24403251, 2013). "Our findings also suggest that RBBP8 served as a protective factor for breast cancer." (PMID 36960071, 2023). "In total, 11 DNA repair genes (UBE2A, RBBP8,RAD50, FAAP20, RPA3, ENDOV, DDB2, UBE2V2,MRE11, RRM2B, andPARP3) were preserved as prognostic genes to estimate risk score, which was applied to establish the prognostic model and stratified breast cancer patients into two groups with high or low risk." (PMID 36713553, 2022). "Accordingly, RBBP8 may prevent breast cancer cells from organ metastasis." (PMID 36713553, 2022). "Accumulating studies propose RBBP8, known to encode the endonuclease CtIP, as a novel susceptibility gene whose functional loss increases sensitivity towards PARP1 inhibition similar to BRCA1 inactivation as, for instance, recently demonstrated in a mice xenograft model of breast cancer." (PMID 29445424, 2018). "However, an association with specific CtIP/RBBP8 haplotypes has been proposed to be a cancer-risk modifier in breast cancer for BRCA1 mutation carriers, but not for ovarian cancer." (PMID 24403251, 2013). "This study developed a signature featuring 8 OARGs (HLA-B, RBBP8, SPRY4, WT1, WWOX, UPRT, PELO, ZNF208) and determined its prognostic and functional implications in breast cancer patients." (PMID 36960071, 2023). "A total of 11 DNA repair genes, namely, UBE2A, RBBP8,RAD50, FAAP20, RPA3, ENDOV, DDB2, UBE2V2,MRE11, RRM2B, andPARP3, were involved in the prognostic model for breast cancer patients." (PMID 36713553, 2022).
breast carcinoma (continued). "The hazard ratio of five genes (RBBP8,PARP3, ENDOV, UBE2V2, and DDB2) was <1, which plays a protective role in developing breast cancer." (PMID 36713553, 2022). "In conclusion, we have performed a retrospective study of the relationships between CtIP/RBBP8 expression levels and cancer prognosis and relapse using paraffin-embedded breast cancer biopsies from a cohort of 384 patients." (PMID 24403251, 2013). "We performed a retrospective analysis of CtIP/RBBP8 and RB1 levels by immunohistochemistry using 384 paraffin-embedded breast cancer biopsies obtained during tumor removal surgery." (PMID 24403251, 2013). "For CtIP (also known as retinoblastoma binding protein 8, RBBP8, ranked at 2), the expression of this gene had been shown to be a novel mechanism for tamoxifen resistance development in breast cancer." (PMID 21799737, 2011). "Despite all the available data, no systematic study of CtIP/RBBP8 expression on breast cancer samples and its correlation with treatment response and disease-free survival has been done." (PMID 24403251, 2013). "We have observed that low or no expression of CtIP/RBBP8 correlates with high-grade breast cancer and with nodal metastasis." (PMID 24403251, 2013). "Whereas we found a strong bias for tumors with normal CtIP/RBBP8 levels to be positive for ER and PR receptors (of 91.5% and 78%, respectively), breast cancers with no CtIP/RBBP8 staining had an almost equal distribution of HR-positive and HR-negative samples." (PMID 24403251, 2013). "The poor prognosis of breast cancer was related to the low or no expression of RBBP8." (PMID 30622325, 2020). "However, even though CtIP/RBBP8 mRNA was found to be overrepresented in certain tumors, we have never observed overexpression at the protein level in breast cancer." (PMID 24403251, 2013). "The expression level ofPARP3, RBBP8, and DDB2 was higher in breast cancer patients without HER2 receptors than in patients positive for the HER2 receptor." (PMID 36713553, 2022). "Our results suggest a strong relationship between no or low expression of CtIP/RBBP8 and poor breast cancer prognosis." (PMID 24403251, 2013).
Seckel syndrome (12 papers, 2011 to 2025). A rare autosomal recessive inherited syndrome caused by mutations in the ATR gene, RBBP8 gene, CENPJ gene, CEP152 gene, CEP63 gene, NIN gene, DNA2 gene, or TRAIP gene. "The highest ranking concepts for the implicit association of RBBP8 and Seckel Syndrome were ATR and cell cycle checkpoint." (PMID 26919047, 2016). "Case 1.4.5 revealed heterozygosity in both partners for likely pathogenic variant in RBBP8 causative of Seckel Syndrome 2 (OMIM # 606744), whereas case 1.4.6 revealed both parents to be heterozygous carriers for a VUS in COL11A2 associated with fibrochondrogenesis 2 (OMIM # 614524)." (PMID 35123515, 2022). "Other forms of Seckel syndrome are caused by mutations in genes associated with cell growth (TRAIP), genomic integrity and repair (ATR, NSMCE2, DNA2, and RBBP8), centrosome function (NIN, CEP63)." (PMID 29504900, 2018). "More recently (January 2011-February 2014), mutations in for example RBBP8, CEP152 and DNA2 were found to cause Seckel syndrome: SCKL2, October 2011; SCKL5, January 2011; SCKL8, February 2014, respectively." (PMID 26919047, 2016).
colorectal cancer (6 papers, 2013 to 2025). A primary or metastatic malignant neoplasm that affects the colon or rectum. "CtIP/RBBP8 microsatellite-induced frameshift mutations have been found in colorectal cancer and endometrial cancer, and point mutations have been observed in some cancer cell lines." (PMID 24403251, 2013). "Mutations in the RBBP8 gene cause tumors such as colorectal cancer and endometrial cancer." (PMID 30622325, 2020). "The long arm of chromosome 18 spans several confirmed and putative tumor suppressors, including Retinoblastoma-Binding Protein 8 (RBBP8), SMAD family members 2 and 4 (SMAD2/4), and deleted in colorectal cancer (DCC)." (PMID 37954063, 2023).
ovarian carcinoma (6 papers, 2013 to 2026). A malignant neoplasm originating from the surface ovarian epithelium. "Deletion of the RBBP8 gene was associated with significantly worse prognosis in ovarian cancer." (PMID 30622325, 2020). "Moreover, RBBP8 deficiency has been associated with increase the susceptibility of breast and ovarian cancer to poly ADP ribose polymerase (PARP) inhibitors in a manner similar to BRCA1 mutations which suggests a possible benefit of difficult to manage MIBC from this approach." (PMID 36076047, 2022).
bladder cancer (5 papers, 2018 to 2022). "Here, we demonstrate that RBBP8 whose unique hypermethylation pattern in human bladder cancer was associated with its gene silencing might serve as a biomarker that can be accessed via urine tests." (PMID 29445424, 2018). "Thus, beyond a possible prognostic or predictive relevance of RBBP8 loss in human cancers, its promoter methylation may be suitable for diagnostic or monitoring applications in bladder cancer." (PMID 29445424, 2018). "Since a RBBP8 methylation frequency of approximately 40% is found in bladder cancer, sensitivity is limited." (PMID 29445424, 2018). "A multiple t tests using the Holm correction for multiple comparison analysis confirmed a significantly increased methylation frequency of RBBP8 in bladder cancer compared to all other tested tumor entities (p < 0.019)." (PMID 29445424, 2018). "DAC treatment without TSA supplementation already triggered an increase in RBBP8 mRNA expression in RT4 bladder cancer cells." (PMID 29445424, 2018). "RBBP8 was almost exclusively hypermethylated in bladder cancers and was detectable by a non-invasive approach in urines from bladder cancer patients." (PMID 29445424, 2018). "RBBP8 methylation was detectable in urine samples of bladder cancer patients achieving a sensitivity of 52%, at 91% specificity." (PMID 29445424, 2018). "As previously observed in primary bladder cancer, RBBP8 promoter methylation detected in urines strongly correlates with high-grade tumors." (PMID 29445424, 2018). "Overall, 42 bladder carcinomas were compared evaluating the average RBBP8 protein expression in a semi-quantitative manner (for cohort characteristics)." (PMID 29445424, 2018). "Hypermethylation of RBBP8 has been previously detected as biomarker for bladder cancer patients." (PMID 36076047, 2022). "Additionally, the single RBBP8 marker was able to distinguish bladder cancer patients from patients with neoplasms of another urological origin (malignant control set) with high specificity (90.8%, AUC 0.686, 95% CI 0.583–0.789)." (PMID 29445424, 2018). "Further investigation of mechanisms involving RBBP8 may deliver novel therapeutic options for bladder cancer patients, finally highlighting RBBP8 as a predictive biomarker as well." (PMID 29445424, 2018). "RBBP8 methylation was clearly increased, up to 88%, in urines from bladder cancer patients." (PMID 29445424, 2018). "As RBBP8 is highly methylated in bladder tumor tissue, RBBP8 methylated DNA might also be detectable in urine samples from bladder cancer patients." (PMID 29445424, 2018). "Interestingly, RBBP8 was almost exclusively methylated in bladder cancer." (PMID 29445424, 2018). "The TCGA−BLCA dataset showed that the expression of RBBP8 and MSH4 was significantly lower in bladder cancer cases as compared to normal samples (p < 0.001)." (PMID 36076047, 2022). "In bladder cancer, 3 out of these identified 39 DDR genes, i.e., SLX1A, ERCC1, and RBBP8, exhibited hypermethylation over 15%." (PMID 29445424, 2018). "Using MSP, a methylated RBBP8 promoter was detected in two (RT4 and RT112) out of four bladder cancer cell lines which derived from stage 2 and higher grade bladder tumors, while RBBP8 was unmethylated in normal urothelial cells (UROtsa)." (PMID 29445424, 2018). "Strong RBBP8 promoter methylation in RT4 (median methylation level 90.5%) and RT112 bladder cancer cells (median methylation level: 28.5%) was confirmed by using bisulfite-pyrosequencing covering the MSP product sequence." (PMID 29445424, 2018). "In all bladder cancer cell lines (RT4, RT112, J82, and EJ28), RBBP8 mRNA was lower expressed than in normal UROtsa cells." (PMID 29445424, 2018). "Furthermore, GEO13507 dataset showed that RBBP8 and MSH4 were differentially expressed in bladder cancer cases compared normal tissues by 1.82 and 1.88 fold, respectively (p < 0.001)." (PMID 36076047, 2022).
bladder cancer (continued). "RBBP8 hypermethylation predicted longer overall survival (OS) and was found in 2/4 bladder cancer cell lines but not in any of 33 cancer cell lines from entities with another origin like prostate." (PMID 29445424, 2018). "In turn, RBBP8 mRNA was not further inducible by DAC/TSA in J82 bladder cancer cells harboring an unmethylated RBBP8 promoter." (PMID 29445424, 2018). "Accordingly, RBBP8 methylation significantly discriminates between bladder cancer patients and non-malignant patients with a sensitivity of 51.9% and a specificity of 90.9% (AUC 0.730, 95% CI 0.616–0.844)." (PMID 29445424, 2018). "Hence, we provide a novel biomarker candidate, i.e., RBBP8, which has previously been shown to sensitize tumor cells for PARP1 inhibitors and which may improve entity-specificity for monitoring, early detection, and clinical management of bladder cancer in a urine biomarker panel." (PMID 29445424, 2018).
osteosarcoma (4 papers, 2011 to 2025). A usually aggressive malignant bone-forming mesenchymal neoplasm, predominantly affecting adolescents and young adults. "Importantly, gene mutations in both BLM and RBBP8 are associated with increased risks of tumor formation, including osteosarcoma." (PMID 33519915, 2020).
gastric cancer (3 papers, 2021 to 2025). A primary or metastatic malignant neoplasm involving the stomach. "Through inducing the histone deacetylation of p21 promoter and inhibiting p21 transcription via CtBP and BRCA1, RBBP8 serves a vital regulator in gastric cancer." (PMID 37656243, 2023).
lung adenocarcinoma (3 papers, 2018 to 2023). A carcinoma that arises from the lung and is characterized by the presence of malignant glandular epithelial cells. "A patient with lung adenocarcinoma and with a homozygous stop-gain mutation in BARD1 (G320*) and a duplication event in RBBP8 (e3–4 duplication) was also classified as HRD by HRDetect but not by CHORD." (PMID 36964191, 2023).